BRCA1 (BRCA1 DNA repair associated)
Diseases named in the same sentence as BRCA1 in open-access papers (continued):
Sharing a sentence is not in itself a finding about the gene and the disease.
tumor (continued). "Therefore, it remains unclear whether BRCA1 promoter methylation, which may be more heterogeneous in the different tumor cells, influences the DNA methylation profile in the same manner as germline BRCA1 pathogenic mutations." (PMID 26727311, 2015). "However patients with a BRCA1/2 mutation have an increased sensitivity to agents that cause DNA damage through double stranded breaks or DNA cross-links, such as platinum agents due to the genetic basis of their tumours." (PMID 25526776, 2014). "In addition, the S6 mutations reduce tumor formation induced by Brca1-deficiency in mice." (PMID 24831086, 2014). "Interestingly, both genes are located at 17q11.2 and show lowest expression in BRCA1 tumors, which could indicate that loss of this region may be associated with the development of the basal-like BRCA1 tumor type." (PMID 23704984, 2013). "The BRCA1 gene has almost 2000 described sequences changes, including mutations leading to changes in the reading frame by deletion or insertion, missense mutations, inframe deletions, nonsense and various types of sequence variants and polymorphisms (Breast Cancer Information Core)." (PMID 23941236, 2013). "Thus, some BRCA1 functions are linked to the regulation of transcription, although which of these may contribute to tumor suppression remains unclear to date." (PMID 23802008, 2013). "In the current study, we identified a transcriptional signature associated with BRCA1/2 status that distinguished BRCA1/2-associated tumors from negative tumors and suggested distinct biological processes involved in driving transformation in these tumor groups of young patients." (PMID 23469205, 2013). "Loss of BRCA1 activity may also alter tumor phenotype through deregulation of the EMT inducer SLUG." (PMID 23173005, 2012). "There was early concern that BRCA1/2-associated tumors were particularly radiosensitive, and because of the role of these genes in DNA repair, that radiation therapy may stimulate additional tumor formation." (PMID 22295226, 2011). "Emerging evidence suggests that tumours may be characterized by a relative level of BRCA1 deficiency at both the mRNA and protein level, resulting in BRCA1 having a potentially broader clinical relevance as a prognostic and predictive marker for patients with sporadic disease." (PMID 22312502, 2011). "Hence, we hypothesized that deficiencies in BRCA1 would cause increased chromosomal instability in a tumor cell due to impaired DNA repair pathways and NHEJ dysfunction." (PMID 22032724, 2011). "However, tumour cells that are deficient in the tumour suppressors BRCA1 and BRCA2 proteins, which are important for efficient repair of DSBs by homologous recombination repair, use alternative DNA repair pathways such as base excision repair to compensate for nonfunctional homologous recombination." (PMID 24281034, 2010). "Furthermore, it may also partly account for the increased genomic instability described in BRCA1-associated tumours." (PMID 19724277, 2009). "Although the reason for this inconsistency is still unclear, it could point to a species difference: the lifespan of a mouse might simply be too short or the rate of LOH might be too low for heterozygous Brca1 mice to acquire additional mutations necessary for tumour development." (PMID 19904273, 2009). "Therefore, PARP inhibition may be synthetically lethal with BRCA1 loss and serve as a specific therapy for BRCA1-mutated tumours." (PMID 19904273, 2009).
tumor (continued). "It remains to be established, however, whether silencing of these genes is responsible for the selective advantage of EZH2 overexpression in BRCA1-deficient tumor cells, and whether these genes include more classical tumor-suppressors or specific differentiation factors." (PMID 19709408, 2009). "The discrepancy may at least in part be resolved by the hypothesis that the timing of BRCA1 methylation will influence tumour phenotype; the earlier in tumorigenesis methylation occurs, the greater the similarity to tumours arising from germline BRCA1 mutations." (PMID 18269736, 2008). "Furthermore, limited evidence from MSI analysis of a single tumour carrying a BRCA1 W1837R variant has been interpreted to suggest that missense mutations in the BRCT domain may present with a microsatellite-unstable tumour phenotype." (PMID 18036263, 2007). "There is evidence to suggest that epigenetic changes and preferential methylation of sites within the BRCA1 promoter region can lead to this down-regulation of expression; however, collectively, these mechanisms are implicated in only a small percentage of sporadic tumours." (PMID 17663789, 2007). "In addition, we found a considerable proportion of the BRCA1 methylated tumours (7 of 13) to be of grade 3, with only one tumour of grade 1, as well as an indication of an association between BRCA1 methylation and an early age of onset (P = 0.0898) as previously reported by Wei and colleagues." (PMID 16846527, 2006). "The type of mutation in the BRCA1 gene may affect the timing of the diagnosis of the disease, the response to environmental exposure causing DNA damage, the efficiency of DNA repair, and the frequency of somatic mutations developing in the tumor." (PMID 16229746, 2005). "The concept — that the loss of BRCA1 or BRCA2 can act as a trigger for cell death and thereby contribute to tumor suppression — has been proposed previously." (PMID 40841483, 2026). "To assess the potential artificial synthetic lethality and overcome PARPi resistance by inhibiting FASN activity in-vivo, we tested the combination synergism between 5HLS and talazoparib on the BRCA1 wild-type TNBC xenograft tumor." (PMID 41158759, 2026). "BRCA1 mutations were associated with CD8+ Trm expansion, whereas BRCA2 mutations were linked to tumor CD4+ Trm expansion and peripheral T/NK cell cytotoxicity." (PMID 42189716, 2026). "Beyond predicting PARP inhibitor sensitivity, BRCA1/2 alterations affect the tumor microenvironment, resulting in increased tumor-infiltrating lymphocyte density and altered T-cell function." (PMID 41512445, 2026). "In vivo, tumours expressing Δexon11 BRCA1 exhibited only partial resistance to olaparib compared to those expressing full-length BRCA1." (PMID 41595228, 2026). "For instance, it was previously estimated that ≥20%–30% of BRCA1 expression is enough to confer tumor suppressor activity." (PMID 41230741, 2026). "Particularly, 75.0% of non-BRCA1/2 HR-related genes were detected in off-tumor patients, suggesting their possible but currently unestablished contribution to tumorigenesis." (PMID 40926019, 2026). "Several genes, including p16, Rb, PTEN, ZNF154 and BRCA1, have been identified as hypermethylated in corresponding tumours." (PMID 41510594, 2026). "Genomic profiling of OSCC samples has identified occasional BRCA1 and BRCA2 mutations, suggesting their contributions to tumor onset and progression." (PMID 40224184, 2025).
tumor (continued). "BRCA1 is a tumor-suppressor gene and a key player in several cellular pathways, including DNA repair, gene transcription, cell differentiation, chromatin structures, and cell cycle regulation, which are defective if BRCA1 gene function is lost." (PMID 41283387, 2025). "In TNBC, miR-199a 3p acts as a tumor suppressor by targeting BRCA1, impairing DNA repair, and decreasing proliferation and migration—additionally enhancing sensitivity to cisplatin and PARP inhibitors." (PMID 41009685, 2025). "Similarly, other TFs that regulate genes like BRCA1/2 (BRCA1/2 DNA Repair Associated), essential for homologous recombination, may lead to genomic instability if dysregulated, increasing the risk of mutations and tumor progression." (PMID 41155227, 2025). "BRCA1/BRCA2 reversion mutations, detected in 20–40% of resistant HGSOC cases via circulating tumor DNA (ctDNA), restore HR function, negating PARPi sensitivity." (PMID 40864792, 2025). "While only 5–10% of cases are hereditary, primarily linked to germline mutations in the BRCA1 and BRCA2 genes, the majority are sporadic, caused by the accumulation of somatic mutations over time, leading to uncontrolled cell growth and tumor development." (PMID 40004528, 2025). "The functional investigation of METTL1 and BRCA1 revealed that METTL1 mediated the upregulation of BRCA1 through m7G modification, thereby promoting cell proliferation and tumor growth in HGSOC." (PMID 41430564, 2025). "Key tumor suppressor genes, including BRCA1, p16, and RASSF1A, often exhibit hypermethylation, leading to their silencing and subsequent loss of tumor-suppressive functions." (PMID 41048999, 2025). "First, we built a cohort of 63 patients with TNBC (including 32 BRCA1-wildtype and 31 BRCA1-mutant tumor samples) and optimized an immunohistochemistry assay to evaluate nuclear vs. cytoplasmic ADAR1p150 expression in tumor cells." (PMID 40730818, 2025). "Preclinical studies have demonstrated that BRCA1/2-mutant tumor cells are highly sensitive to PARP inhibitors due to defects in homologous recombination repair (HRR)." (PMID 40481929, 2025). "HRD scoring is typically based on several key indicators, including BRCA1/2 mutations, loss of heterozygosity (LOH), and tumor mutational burden (TMB)." (PMID 40395324, 2025). "In Cohort A, comprised of patients with core HRD (BRCA1/2 or PALB2 mutations), we observed high tumor response rates, durable disease control, and encouraging long-term survival." (PMID 40951294, 2025). "Loss-of-function mutations in HRR-related genes, especially BRCA1 and BRCA2, sensitize tumor cells to DNA-damaging agents and PARPi, providing the biological rationale behind HRD testing in clinical practice." (PMID 40507252, 2025). "RNA-seq analysis of this third case demonstrated low expression of BRCA1 in the tumor (patient BRCA1 expression: 1.76 transcripts per million (TPM) compared with the cohort median TPM 6.3 [range 1.13–16.94])." (PMID 40072012, 2025). "The BRCA1 Associated RING Domain protein, BARD1 [OMIM 601593], is required for the BRCA1 tumor suppressor to fold and function." (PMID 41282735, 2025). "One patient carried a confirmed germline BRCA1 mutation (c.5266dup, p.Gln1756ProfsX74; LOH score: 29%), while the other had a somatic BRCA1 mutation (c.1789G>T, pGlu597*; LOH score: 38%), detected only in the tumor tissue." (PMID 41323499, 2025). "Subsequent studies confirmed NBR2’s identity as a lincRNA and have begun to elucidate its intricate roles in tumor biology, revealing its involvement in tumor suppression alongside BRCA1." (PMID 39997609, 2025). "PARP inhibitors are effective at killing tumor cells which lack the tumor suppressor activity of BRCA1/2 through synthetic lethality." (PMID 41375064, 2025).
tumor (continued). "Tumor classified as subtype 1 had higher mutation rate, HRD score and pathological tumor infiltrating lymphocyte score, lower BRCA1 expression and were less likely from older patients or those with higher body mass index (BMI; P ≤ 0.05)." (PMID 40858906, 2025). "We observed the upregulation of genes associated with positive anti-tumor activity, including NR3C1, BRCA1, BRCA2 and SFN." (PMID 40043049, 2025). "PARPis show strong efficacy in HRD tumours, but resistance develops through mechanisms like BRCA restoration or alterations in replication fork stability, and loss of BRCA1 promotes methylation, which can restore HR function." (PMID 40141188, 2025). "Combination treatment with PARP inhibitors (e.g., olaparib or niraparib) and anti-PD-L1 therapy has demonstrated superior tumor regression in BRCA1/2-mutant models compared with either monotherapy." (PMID 41373427, 2025). "In BRCA1/2-mutant tumor models, this combination has demonstrated superior tumor regression compared to either monotherapy." (PMID 41373427, 2025). "Inducible 545 cells, isolated from a TNBC tumor of a Brca1-MSK mouse, were injected into mice with mammary fat pad implantation." (PMID 41318657, 2025). "In HR‐deficient tumor cells, where DSB repair relies on compensatory NHEJ, genomic instability is exacerbated, driving the synthetic lethality associated with BRCA1 deficiency and PARP inhibition." (PMID 41473689, 2025). "In approximately half of the EOC patients with a BRCA1/2 PV detected in the tumor, the PV is of germline origin and their relatives are invited for counseling and testing, regardless of the cancer history of the relatives." (PMID 40323485, 2025). "Here, we investigated the role of the E3 ubiquitin ligase SCF (β-TrCP) in cisplatin resistance in different tumor cell lines, analyzing its role in the stability of BRCA1 and CtIP, proteins involved in DNA damage repair by homologous recombination." (PMID 40720252, 2025). "Increased activation of this pathway, observed in our study through elevated AKT1 and BRCA1 expression, can lead to enhanced tumor cell survival and resistance to apoptosis." (PMID 40584614, 2025). "BRCA1 and BRCA2 are tumour suppressor genes that encode proteins involved in the double-strand break DNA repair mechanism by homologous recombination." (PMID 41335382, 2025). "Tumour testing of HGSOC resection specimens can detect BRCA1/2 Tier I/II and American College of Medical Genetics (ACMG1/2) variants reliably while identifying somatic variants independent of germline status." (PMID 41300712, 2025). "Evaluating the differences in gene expression in various tumor types is critical to elucidate further the functional implications of BRCA1 and BRCA2 in canine tumors." (PMID 40004231, 2025). "In vivo studies showed that TGF-β1 knockdown significantly inhibited tumor growth, and this effect was achieved by upregulating BRCA1 expression and Smad3 phosphorylation." (PMID 40138287, 2025). "Finally, we think that our study (limited to missense variants in two functional domains of the tumor-suppressor gene BRCA1) illustrates some general principles and recommendations that might be relevant in evaluating PP3/BP4 computational evidence in other proteins." (PMID 40233743, 2025). "Tumor and treatment characteristics in BRCA1 and BRCA2 carriers according to hormone receptor status are reported in the Data Supplement, and those according to the type of first DFS events are reported in the Data Supplement." (PMID 39993249, 2025). "The loss of BRCA1 and BRCA2 leads to the impairment of homologous recombination repair functions, rendering tumor cells unable to effectively repair DNA damage, consequently causing genomic instability and tumor progression." (PMID 40370464, 2025).
tumor (continued). "Expression of miR-335 can modulate the proliferation and invasion of tumor cells by affecting genes such as BRCA1, ER-α, and IGF1R." (PMID 41009512, 2025). "If tumor cells activate the homologous recombination repair pathway by upregulating key repair proteins (such as BRCA1/2, RAD51, etc.), they can efficiently repair these serious damages and thus escape chemotherapy induced cell apoptosis." (PMID 41293424, 2025). "METTL1 enhanced BRCA1 expression via m7G modification, boosting cell proliferation and tumor growth." (PMID 41430564, 2025). "Key vulnerabilities, such as BRCA1/BRCA2 mutations, have been exploited with PARP inhibitors, leveraging synthetic lethality to selectively kill tumor cells and improving patients’ survival." (PMID 40422251, 2025). "Out of the 15 P/LPGVs in BRCA1 identified on germline sequencing, 13 were detected on the tumor sequencing profile, resulting in a concordance rate of 86.7%." (PMID 41465149, 2025). "PCLAF+ DC, as an immature DC subpopulation enriched in the BRCA1-WT group, induced the proliferation of Treg cells through interacting with Tumor cells." (PMID 40904511, 2025). "In the Netherlands, BRCA1/2 testing changed to a tumor-first approach to efficiently identify both somatic and germline pathogenic variants in all patients." (PMID 40323485, 2025). "The resulting changes in BRCA1/2 expression were evaluated using qPCR, and tumor profiles were assessed through microscopy and immunofluorescence." (PMID 41373491, 2025). "BARD1 is a tumor‐related gene that interacts with BRCA1, forming a complex with E3 ubiquitin ligase." (PMID 39865406, 2025). "The Abraxas/BRCA1-A complex plays a critical role in the recruitment of BRCA1 to DSBs and promotion of BRCA1 dimerization at DSBs for tumor suppression." (PMID 41359628, 2025). "We labelled BRCA1/2‐defective tumours as HRD+ as this is the most common mechanism that produces the phenotype." (PMID 40260608, 2025). "Initial studies suggested that BAP1 primarily localizes to the nucleus, where it interacts with BRCA1 to enhance its tumor-suppressive function." (PMID 40918144, 2025). "Inactivation of both BRCA1 and BRCA2 is associated with homologous recombination deficiency (HRD) and, consequently, tumor sensitivity to PARP inhibitors, platinum compounds, and other drugs capable of inducing DNA double-strand breaks." (PMID 40547808, 2025). "A total of 100 (87.7%) out of 114 participants who had sufficient tumor purity underwent HRD testing, including tissue BRCA1/2 mutation." (PMID 41193417, 2025). "Tumor DNA was extracted from FFPE samples, followed by next-generation sequencing to detect deleterious or suspected deleterious variants in BRCA1/2 genes." (PMID 40958873, 2025). "Promoter hypomethylation of tumor suppressor genes, such as BRCA1, promotes tumor initiation and progression." (PMID 40358524, 2025). "Conversely, BRCA1 deficiency leads to increased GPX4 levels, inhibiting ferroptosis and promoting tumor growth." (PMID 40539051, 2025). "BRIP1, also known as BACH1 or FANCJ, interacts with BRCA1 and plays a role in DNA repair and tumor suppression." (PMID 41473825, 2025). "All BRCA1 missense and synonymous SNVs we observed in the GL-1 cells were also found in canine normal and tumor mammary samples." (PMID 40616061, 2025). "The first major trait of metabolic reprogramming of BRCA1-expressing tumor cells in this study was bioenergetic metabolism alteration." (PMID 40863152, 2025).